ADAMDEC1 (ADAM like decysin 1)
Diseases named in the same sentence as ADAMDEC1 in open-access papers (continued):
Sharing a sentence is not in itself a finding about the gene and the disease.
chordoma (1 paper, 2025). Chordomas are rare malignant tumors arising from embryonic remnants of the notochord in axial skeleton. "The expression analysis identified significant downregulation of SPOCK3, NRK, MYH8, DLK1 and SLN, alongside upregulation of HLA-DQA1, GDA, CXCL11, CXCL9 and ADAMDEC1 in chordomas." (PMID 40386066, 2025).
colorectal adenoma (1 paper, 2025). An adenoma that arises from the colon or rectum. "Therefore, we verified the co‐localization of BDKRB1 and ADAMDEC1 in pathological sections of patients with colorectal adenoma." (PMID 40859429, 2025).
cystic fibrosis (1 paper, 2025). Autosomal recessive disorder caused by pathogenic variants in the CFTR gene (cystic fibrosis transmembrane conductance regulator), which encodes a chloride and bicarbonate channel expressed in epithelial cells, and follow the diagnosis criteria. "This revealed an additional 67 significantly differentially expressed protein groups between cystic fibrosis patients and healthy individuals, including GUCA2A, ADAMDEC1, and FABP1 (upregulated) and GP2 (downregulated)." (PMID 40425748, 2025).
gastric cancer (1 paper, 2021). A primary or metastatic malignant neoplasm involving the stomach. "Deficiency of ADAMDEC1 of gastric cancer cell also associated with high expression of PD-L1 and Jurkat T cell apoptosis." (PMID 34893046, 2021). "In the current study, ADAMDEC1 was confirmed to be associated with favorable prognosis in gastric cancer." (PMID 34893046, 2021). "In vitro, ADAMDEC1 was confirmed as a potential protein in regulating proliferation and migration of gastric cancer cell." (PMID 34893046, 2021). "In addition, we found that depletion of ADAMDEC1 increased PD-L1 expression in gastric cancer cell." (PMID 34893046, 2021). "Furthermore, silencing ADAMDEC1 of gastric cancer cells promoted apoptosis of Jurkat T cells." (PMID 34893046, 2021).
ovarian carcinoma (1 paper, 2019). A malignant neoplasm originating from the surface ovarian epithelium. "High expression of GJB2, S100A2, SPOCK2, TGM1or EPS8 indicated a poor OS of patients with ovarian cancer, whereas ovarian cancer patients with higher expression of ADAMDEC1, CHEK1, EGFL6, FAM181A, FOXA2, LYPD1, PART1 or XPR1 possessed better OS." (PMID 31794425, 2019). "For RFS of patients with ovarian cancer, SPOCK2 and FAXDC2 were unfavorable prognostic biomarkers but ADAMDEC1, CCNA2, FAM181A, FOXA2, LRRTM1, NEIL3 and XPR1 were favorable prognostic biomarkers." (PMID 31794425, 2019).
psoriasis (1 paper, 2024). An autoimmune condition characterized by red, well-delineated plaques with silvery scales that are usually on the extensor surfaces and scalp. "The results demonstrated that CCL20, ADAMDEC1, and CXCL13 exhibited strong diagnostic performance in both BC and psoriasis." (PMID 38605947, 2024).
rectal cancer (1 paper, 2022). A primary or metastatic malignant neoplasm that affects the rectum. "Furthermore, the studies revealed that ADAMDEC1, which is required for the interaction of dendritic cells and germinal center T-helper cells, was involved in protein metabolism and cell adhesion during preoperative radiotherapy for rectal cancer." (PMID 35664306, 2022).
sarcoidosis (1 paper, 2020). Sarcoidosis is a multisystemic disorder of unknown cause characterized by the formation of immune granulomas in involved organs. "MMP12 and ADAMDEC1 are two previously reported potential pathogenic mediators of lung damage and remodeling most highly over-expressed in sarcoidosis patients." (PMID 33097805, 2020). "Among 20 similar signature genes shared by TB and sarcoidosis identified through RNA-Seq analysis, we further confirmed similar over-expression of MMP12, ADAMDEC1, CCL19, CXCL13, and CYP27B1 in TB and sarcoidosis lungs." (PMID 33097805, 2020).
uterine infection (1 paper, 2009). "The uterine infection was also associated with a marked upregulation of several ADAM and ADAMTS metalloproteases, primarily ADAMTS2, ADAMTS5, ADAMDEC1 and ADAM28." (PMID 19956711, 2009).
viral infection (1 paper, 2016). "The primary B cell infection with this virus unequivocally demonstrated that the RBPJ BM EBNA3C virus is completely unable to repress ADAM28, ADAMDEC1 and COBLL1, providing compelling evidence that the EBNA3C:RBPJ interaction is essential in the context of viral infection." (PMID 26751214, 2016).
tumor (20 papers, 2003 to 2025). "The results indicated that increased ADAMDEC1 expression was associated with a higher purity of READ tumor cells in B and dendritic cells." (PMID 35664306, 2022). "ADAMDEC1 plays a pivotal role in immune escape and regulating the tumor microenvironment in SKCM, particularly affecting immune-related gene expression." (PMID 40547036, 2025). "Tissue-specific subsets included CXCL8 + breast fibroblasts [most abundant subset (>85%) in normal breast tissue], NPNT+ (alveolar) lung fibroblasts and F3+/ADAMDEC1 + colonic/gastric fibroblasts (all found in normal and tumour samples)." (PMID 39757146, 2025). "A total of five potentially targetable tumor antigens were identified (PTPRC, SIGLEC10, CARD11, LILRB1, ADAMDEC1); high antigen expression was associated with prolonged OS and DFS, as well as higher tumor infiltration by antigen-presenting cells." (PMID 36992220, 2023). "Overexpression of ADAMDEC1 is correlated with tumor progression, inflammation, immunotherapeutic response, and a poor prognosis in many cancers." (PMID 35741697, 2022). "ADAMDEC1 has been reported to participate in the maintenance of GBM cancer stem cells (GSCs), while targeted silencing of ADAMDEC1 reduced tumor cell proliferation." (PMID 36172139, 2022). "We found the expression level of ADAMDEC1 to be as follows: GBM > LGG > normal; ADAMDEC1 showed that the higher the expression, the higher the malignancy of the tumor and the shorter the survival period." (PMID 36172139, 2022). "Tumor mutational burden (TMB) has received attention in immunotherapy, and ADAMDEC1 is an important biomarker for predicting response to antibody therapy." (PMID 36172139, 2022). "In both studies, increased level of ADAMDEC1 was demonstrated to play a crucial role in tumour division and progression." (PMID 31467500, 2019). "This study identified a metastatic susceptibility locus within a 2 Mb region of 8p21-22, which appears to be a "hot-spot" for genes with a role in carcinoma development and revealed ADAMDEC1 as a potential tumour suppressor." (PMID 18590575, 2008). "Notably, ADAMDEC1 expression in CAFs was significantly correlated with T-cell infiltration within the tumor microenvironment." (PMID 40759242, 2025). "As a potential tumor antigen, ADAMDEC1 may serve as a target for mRNA vaccines, with patients exhibiting immune subtype IS2 potentially more responsive to these vaccines." (PMID 40547036, 2025). "This study suggested that ADAMDEC1 may be an epithelial intrinsic soluble factor that promotes apical extrusion of RasV12 cells, displaying anti-tumour activity, in a phenomenon called “epithelial defense against cancer”." (PMID 31467500, 2019). "ADAMDEC1 mRNA and protein expression decreased during both tumourigenesis and tumour progression." (PMID 18590575, 2008). "Among the nine cell states associated with fibroblasts, five (ADAMDEC1+ fibroblast, BMP4+ fibroblast, intestinal smooth muscle, myofibroblast, PI16+ fibroblast) were identified as NAT-enriched, and three (WNT5A+ fibroblast, pericyte, desmoplastic fibroblast) were identified as tumor-enriched." (PMID 40032993, 2025). "In addition, we also explored the molecular mechanism of ADAMDEC1 in tumor progression." (PMID 36172139, 2022). "In contrast, ADAMDEC1+ Fibro, C3+ Fibro, CFD+ Fibro, DPT+ Fibro, Proliferating Fibro, and Myo Fibro were present in both tumor and normal tissues and were therefore classified under the Fibro group." (PMID 41031085, 2025). "Desmoplastic and WNT5A+ inflammatory fibroblasts were indicated as the sources of tumor-enriched ECM proteins, while ADAMDEC1+ expressing fibroblasts and PI16+ expressing fibroblast were identified as the sources of NAT-enriched ECM proteins." (PMID 40032993, 2025).
tumor (continued). "In addition, CAF-specific ADAMDEC1 IHC score was inversely correlated with multiple unfavorable clinicopathological parameters, such as increased tumor invasion depth, nodal and distant metastases, poor cell differentiation, perineural invasion, and increased frequency of tumor budding." (PMID 40759242, 2025). "Herein, we found that 5 genes (Shisa3, PADI1, LRP2, ANGPTL4 and ALOX15B) were upregulated and 4 genes (CXCL9, ADAMDEC1, SCGB1A1/CC10, HLA-G) were downregulated in PR tumor tissues compared to SD tumor tissues." (PMID 31801598, 2019). "For example, ADAMDEC1+ fibroblasts, PI16+ fibroblasts, and IgA plasma appear to be enriched in NAT tissues, in contrast to desmoplastic fibroblasts, macrophages, Treg cells, and IgG plasma, which exhibit a higher proportion in tumor tissues." (PMID 40032993, 2025). "Recently, ADAM Like Decysin 1 (ADAMDEC1) was discovered as a novel target in GBM and is overexpressed by GSCs, which regulate stem cell proliferation and sphere formation, and promote tumor growth through an ADAMDEC1-FGFR1-ZEB1 signaling loop." (PMID 33670551, 2021).
cancer (13 papers, 2008 to 2025). A tumor composed of atypical neoplastic, often pleomorphic cells that invade other tissues. "More research is needed to determine the associations between ADAMDEC1 and immune response and associations with survival for cancers." (PMID 33842346, 2021). "Furthermore, Epstein–Barr virus (EBV) (a herpesvirus) has been shown to induce the suppression ADAMDEC1 which contributes to the formation of EBV-associated cancers." (PMID 36873940, 2023). "As anticipated, cancer tissues rich in ADAMDEC1-positive CAFs also contained significantly higher counts of CD3(+), CD4(+), and CD8(+) T cells." (PMID 40759242, 2025). "Immunohistochemistry showed that key markers identifying this putative Tr-CAF subset—CXCL14, ADAMDEC1, EDNRB, and PROCR—were predominantly localized to fibroblasts within normal colonic mucosa and less frequently in cancer-associated fibroblasts (CAFs)." (PMID 40759242, 2025). "Some of the significant cancer hallmark terms are epithelial-mesenchymal transition (MSX1, CXCL12, SCG2, SLIT2), KRAS signaling up (F13A1, ADAMDEC1), inflammatory response (CCL5, VIP), IL-6/JAK/STAT3 signaling (CXCL13)." (PMID 35486660, 2022). "This gene codes for ADAM like decysin 1, a protein that plays an important role in cancer prevention and intestinal inflammation in humans." (PMID 32928114, 2020). "ADAMDEC1 + /CCL8 + and CXCL14 + fibroblasts were preferentially co-localized with the IgG + plasma cells, in accordance with the observed presence of CXCL14 + cancer-associated fibroblast and ADAMDEC1 + /CCL8 + fibroblast in MMRp CRC." (PMID 38110959, 2023). "We assessed the correlation between ADAMDEC1 and cancer immune cell infiltration." (PMID 36172139, 2022). "Moreover, ADAMDEC1 has also been reported to contribute to the development of cancer." (PMID 36172139, 2022). "In cancer stem cells, ADAMDEC1 solubilizes FGF2 to induce FGFR1, upregulating ADAMDEC1 expression to maintain its stemness." (PMID 35379209, 2022). "From a functional perspective, a couple of markers demonstrated interesting biology (MARCO and ADAMDEC1) deserve more in-depth investigation, especially validation in other cancers and non-cancer-related disease, disorders and syndromes." (PMID 31467500, 2019). "However, the role of ADAMDEC1 and MMP2 in cancer is still unclear." (PMID 36172139, 2022).
infection (2 papers, 2016). The state of being infected such as from the introduction of a foreign agent such as serum, vaccine, antigenic substance or organism. "Adamdec1-/- mice lost a greater proportion of their body weight after S. typhimurium inoculation compared with the wild type and, at 48h post infection, 55% of the knockout compared with only 11% of the wild-type mice had succumbed to the infection." (PMID 27226416, 2016). "It is plausible that ADAMDEC1 may also play an important role in human intestinal immunity and protection against the development of infection and chronic inflammation." (PMID 27226416, 2016). "Infections with wild type, Rev and EBNA3B KO viruses resulted in a reduction of both ADAM28 (2–3 log fold) and ADAMDEC1 (1–2 log fold) levels of mRNA, over a period of 30 days after infection." (PMID 26751214, 2016). "Consistent with the results of the luciferase reporter assays and the ChIP studies, infection with the RBPJ BM EBNA3C virus was unable to repress ADAM28, ADAMDEC1 or COBLL1." (PMID 26751214, 2016). "Increased sensitivity to C. rodentium in mice lacking Adamdec1 may result in an increase in systemic infection." (PMID 27226416, 2016).
ADAMDEC1 also shares sentences with these, for which no sentence is quoted: pulmonary sarcoidosis (3 papers); bacterial infection (2); anemia (1); atherosclerosis (1); breast carcinoma (1); cervical cancer (1); chronic rhinosinusitis (1); gastric adenocarcinoma (1); glioblastoma (1); ileitis (1); ileocolitis (1); inflammatory bowel disease (1); intestinal inflammation (1); lung carcinoma (1); lymphoma (1); metastatic tumors (1); nasal polyps (1); osteoarthritis (1); Ovarian tumor (1); polyarteritis nodosa (1); psychiatric disorder (1); Rectal prolapse (1); ulcerative colitis (1); uveitis (1).